THY1 (Thy-1 cell surface antigen)
Diseases named in the same sentence as THY1 in open-access papers (continued):
Sharing a sentence is not in itself a finding about the gene and the disease.
pneumoconiosis (1 paper, 2022). An occupational lung disorder caused by inhalation of dust particles. "Thy-1 DNA methylation has been extensively studied in other pulmonary fibrosis diseases, and an increase in its methylation plays an important role in pneumoconiosis." (PMID 35096264, 2022).
prion disease (1 paper, 2019). A transmissible disease that is caused by a protein that is able to induce abnormal folding of normal cellular proteins, leading to characteristic spongiform brain changes, which are associated with neuronal loss without an inflammatory response. "In the present study and based on our previous results, we assessed how the substitution of the GPI-SS of PrPC for that of Thy-1 influences the biology of the resulting chimeric PrPCGPIThy-1 in vivo, and how this impacts on the pathophysiology of prion disease." (PMID 30608982, 2019). "To study the role of the GPI-anchor in the pathophysiology of prion diseases in vivo, we have generated transgenic mice where the PrPC GPI-signal sequence (GPI-SS) is replaced for the one of Thy-1, a neuronal protein with a distinct GPI-anchor and membrane localization." (PMID 30608982, 2019).
proliferative glomerulonephritis (1 paper, 2022). A constellation of renal disorders characterized by an increase number of cells in the glomerulus; these disorders generally present with nephrotic syndrome, and generally progress to end stage renal failure over a matter of weeks to years, depending on the etiology. "S1P was shown to be a chemoattractant for primary human monocytes and macrophages in vitro and that employing the S1P receptor functional antagonist fingolimod reduced not only lymphocyte but also macrophage infiltration in acute anti-thy1 mesangio-proliferative glomerulonephritis." (PMID 35409312, 2022).
prostate (1 paper, 2022). "True L.D., Zhang H., Ye M., Huang C.-Y., Nelson P.S., von Haller P.D.,Tjoelker L.W., Kim J.-S., Qian W.-J., Smith R.D., Ellis W.J., LiebeskindE.S., Liu A.Y. CD90/THY1 is overexpressed in prostate cancerassociatedfibroblasts and could serve as a cancer biomarker." (PMID 35342854, 2022).
pulmonary embolism (1 paper, 2013). The obstruction of the pulmonary artery or one of its branches by an embolus, sometimes associated with infarction of the lung. "Mice injected with 2 × 105 to 1 nbsp;× 106 LNGFR+THY-1+ cells expanded in culture, died from pulmonary embolism within a week, and no human cells could be identified in the recipients’ BM." (PMID 24052950, 2013).
restless legs syndrome (1 paper, 2026). A condition that occurs while resting or lying in bed; it is characterized by an irresistible urgency to move the legs to obtain relief from a strange and uncomfortable sensation in the legs. "Our focus on the Thy1 knockout (KO) mouse model stems from the loss of Thy1 expression in individuals with Restless Legs Syndrome (RLS), a neurological disorder." (PMID 41542890, 2026). "Moreover, we demonstrated that Thy1 deficiency leads to specific imbalances in striatal function, which may be relevant to pathologies such as restless legs syndrome (RLS) and may influence behavioral outcomes and responsiveness to therapeutic strategies." (PMID 41542890, 2026).
retinoblastoma (1 paper, 2024). A malignant tumor that originates in the nuclear layer of the retina. "Three genes from the ‘cancer’ and ‘neuro’ group are overlapping (ALK, TLX2, THY1), with THY1 being also directly connected to retinoblastoma." (PMID 39695086, 2024).
Salmonella Infections (1 paper, 2025). Infections with bacteria of the genus SALMONELLA. "Kupz observed that Thy1+NK cells could secret protective IFN-γ in the early stages of Salmonella infection, enhancing the host’s antimicrobial immunity." (PMID 40244063, 2025).
schizophrenia (1 paper, 2019). A major psychotic disorder characterized by abnormalities in the perception or expression of reality. "Therefore, in this study, we generated transgenic mice overexpressing miR-137 (miR-137 Tg mice) with the neuron-specific Thy-1 promoter and examined schizophrenia-related phenotypes in these mice." (PMID 31361772, 2019).
steatosis (1 paper, 2021). Increased lipid within the cytoplasm of cells. "CXCL10 (r = 0.55, P = 2.37 × 10–4) was the most relevant gene with the steatosis grade, and THY1 (r = 0.67, P = 2.04 × 10–6) was the most relevant gene with the fibrosis stage." (PMID 34419146, 2021).
T-cell lymphoma (1 paper, 2015). "Thy-1 (CD90), a marker found to be upregulated in all mature T-cell lymphoma subtypes, is a marker for thymus-derived lymphocytes in mice, with additional implications for being a “cancer stem cell” marker present in both T- and B-malignancies due to its upregulation on immature cells." (PMID 26566034, 2015).
tuberculosis (1 paper, 2024). A chronic, recurrent infection caused by the bacterium Mycobacterium tuberculosis. "Here, we focus on the main signaling pathways involved in the fibroblast formation in the core area of tuberculosis, such as THBS, CD99, MIF, COMPLENENT, CXCL, THY1, and GAS pathways." (PMID 39431015, 2024).
ulnar-mammary syndrome (1 paper, 2018). Ulnar-mammary syndrome (UMS) is a rare developmental disorder characterized by ulnar defects, mammary and apocrine gland hypoplasia and genital anomalies. "We found that the ortholog of TBX3, a gene mutated in ulnar mammary syndrome (UMS), was expressed in all populations except for Thy-1+CD24medCD49fhigh." (PMID 30305179, 2018).
tumor (463 papers, 1987 to 2026). "This methodological rigor is particularly critical in understanding the transcriptional complexity of genes such as THY1, whose expression is highly context dependent and associated with aggressive tumor phenotypes." (PMID 40476057, 2025). "Among potential biomarkers, THY1 has emerged as a strong candidate because of its association with tumor aggressiveness and poor prognosis of GC." (PMID 40476057, 2025). "This context-dependent distribution suggests a stromal-associated role for THY1 within the tumor microenvironment." (PMID 40740771, 2025). "THY1+ fibroblasts exhibit high heterogeneity and are implicated in physiological and biochemical processes such as tumor progression, fibrosis, and cellular proliferation." (PMID 38612311, 2024). "Genes such as COL1A1, COL1A2, and COL3A1, which are implicated in the tumor microenvironment, and immune-related genes, such as THY1, IRF5, and HLA-DRA, exhibited significant expression level changes." (PMID 38672562, 2024). "Conversely, the molecules that were found to be more highly enriched in hTERT-immortalized MSC EVs (i.e., THY-1, Thrombomodulin, Neprilysin) have been associated with reparative, tumor suppressive, and anti-inflammatory properties." (PMID 38786083, 2024). "In contrast, in ovarian cancer and nasopharyngeal carcinoma, high expression of THY1 was associated with tumor suppression and was involved in the suppression of metastasis." (PMID 38254918, 2023). "Our previous studies have shown that THY1 expression is associated with tumor metastasis, and THY1 expression can reduce the invasiveness potential of NPC cells." (PMID 37046850, 2023). "In pathway-based network analysis, DKK3 was directly linked to the THY1 gene, a tumor suppressor gene." (PMID 35599254, 2022). "We found CAFs which highly expressed CTHRC1 (from F04 and F08) and tumor associated macrophages were mediated by a different set of ligand-receptor pairs, including THY1/aXb2 complex, GRN/TNFRSF1A, CD99/PILRA, CD74/MIF, APP/CD74, ANXA1/FPR1, etc." (PMID 35928443, 2022). "THY1 was expressed on mouse tumor-associated lymphatic vessels and blood vessels, displaying log2 fold changes of 1.63 and 1.03 in the spleen and lung of yak." (PMID 35087567, 2021). "In the venous circulation, Thy-1 facilitates the attachment of tumor cells to endothelial cells and has been implicated in metastasis." (PMID 28744021, 2017). "THY1 was identified to be a candidate tumour suppressor gene significantly associated with lymph node metastatic NPC." (PMID 17199893, 2007). "Given this context-dependent regulatory complexity and its strong association with tumor aggressiveness, understanding the transcriptional regulation of THY1 is essential for elucidating the molecular programs that drive invasion, metastasis, and therapy resistance." (PMID 40476057, 2025). "Whereas naïve lung and blood mostly contained differentiated NK cells, metastatic lungs harbored a large cluster of tumor-associated NK cells (Tumor NK) expressing markers of less differentiated NK cells (Emb, Cd27, Ccr2, Cd28, Thy1 or Sell), confirming our flow cytometric data." (PMID 41145419, 2025). "Also, a recent report suggested that THY1-positive tumor cells colocalized with TAMs in GBM, and this was associated with recurrence." (PMID 38515213, 2024). "Thy-1 has been associated with tumor progression in several types of cancers." (PMID 35733855, 2022). "Moreover, clinical characteristics analysis showed that tumor stages were highly associated with THY1 expressions, which were highest in LUAD patients in stage iii." (PMID 35071018, 2021). "The tumor-associated stroma is marked by increased expression of CD90/THY1." (PMID 19737398, 2009). "Additional context-dependent markers include CD90 (Thy-1), podoplanin (PDPN), and tenascin-C (TNC), which are associated with immune modulation, stromal remodeling, and therapy response in specific tumor types." (PMID 41441395, 2025).
tumor (continued). "We performed a Pearson correlation meta-analysis between THY1 and each of the 17 putative regulators, considering both tumor subtypes (diffuse and intestinal) across the three cohorts, to obtain deeper insights into these candidate regulators." (PMID 40476057, 2025). "By integrating bioinformatic predictions with experimental demonstration, this study not only improves our understanding of THY1 regulation but also provides a framework for dissecting the transcriptional networks governing aggressive tumor phenotypes." (PMID 40476057, 2025). "Consistent with this idea, super-resolution confocal imaging of npp tumours in Thy1-YFP mice revealed that tumour-involved WM bundles frequently contained axons with hallmarks of physical injury, including mitochondria-filled varicosities, blebbing and kinks." (PMID 40836081, 2025). "In melanoma and glioblastoma, THY1 overexpression enhances tumor progression and immune suppression by activating cancer-associated fibroblasts (CAFs) and altering immune cell behavior in the tumor microenvironment." (PMID 40817072, 2025). "This study aimed to systematically investigate the upstream regulatory landscape of THY1 and its role in tumor progression." (PMID 40476057, 2025). "In cancer, particularly in carcinomas, THY1 has a context-dependent role, acting as either a tumor suppressor or a promoter of tumor progression, depending on cellular and microenvironmental factors." (PMID 40476057, 2025). "Our work represents a crucial step in elucidating the transcriptional complexity of THY1 and underscores the power of integrating bioinformatic predictions with experimental validation to elucidate fundamental regulatory mechanisms in tumor biology." (PMID 40476057, 2025). "Using differential gene expression analysis between classical Fb subtypes and CAFs, we identified CAF-enriched transcripts, including Postn, Cilp, Loxl1, Thy1, and Pi16, previously associated with CAF identity in various tumor types." (PMID 41223283, 2025). "Genes such as THY1, FN1, and BIRC5 function as diagnostic markers and demonstrate significant correlations with immune cell infiltration and tumour growth, indicating their dual involvement in disease identification and therapeutic intervention." (PMID 40475773, 2025). "This study identifies COL1A1, ITGB1, THY1, and PDGFRA as crucial regulators of UCEC progression, with altered expression linked to tumor behavior and patient survival." (PMID 40817072, 2025). "Two doses of GEM significantly increased the frequency of endogenous tumor infiltrating Thy1.1− CD8+ TPEX (27.5±9.89% in PBS to 66.7±6.21% in GEM; p≤0.0001), but not frequencies in the HA-specific Thy1.1+ CD8+ TPEX." (PMID 39343508, 2024). "CD90 (also known as Thy-1) is a glycoprotein expressed on the surface of both tumor and immune cells." (PMID 39727953, 2024). "For instance, systemic injection of anti-Thy1 liposomal TGF-β inhibitor after pmel-1 Thy1.1+ CD8+ T cell therapy in a B16F10 tumor model showed better tumor regression and total survival rates compared to ACT T cells with and without free drug." (PMID 39030582, 2024). "There was a significant correlation between THY1 expression and tumor purity in 26 types of cancers." (PMID 38819947, 2024). "Taken together, the inhibitory effect of THY1 on NPC metastasis was likely due to the formation of adherens junctions that firmly join the adjacent tumor cells and restrict their mobility when THY1 was present." (PMID 37046850, 2023). "Subsequent quantitative proteomic analysis showed that increased N-glycosylated protein CD90/Thy-1 was detected in the cancer supernatant and CD90+ stromal fibroblasts were identified in the tumor gland using immunohistochemistry." (PMID 36747131, 2023). "In the present study, we further illustrated the mechanism that contributes to the tumor suppressive function of THY1." (PMID 37046850, 2023). "We found that tumor macrophages in HCC displayed the GPI-anchored protein THY-1 on their cell surface." (PMID 37388918, 2023).
tumor (continued). "We hope that these results will contribute to advancement of the current understanding of the THY1 gene in IGC tumor biology and its potential use as a biomarker for the disease." (PMID 38254918, 2023). "By contrast, using a similar experimental setup, depleting NK cells and ILCs (using Thy1 antibody) abolished any protective tumor effects rendered by PD-1 blocking in these murine recipients." (PMID 37098069, 2023). "The current study clearly showed that THY1 can inhibit the NPC tumor invasion by the maintenance of adherens junctions, so the EMT in the tumor cells is suppressed by the presence of THY1." (PMID 37046850, 2023). "The PTPN22 siRNA silencing results showed that the tumor invasion inhibitory activity of THY1 was lost in HONE1-THY1 and HK1-THY1 cells when PTPN22 was depleted." (PMID 37046850, 2023). "We confirmed the presence of THY-1 protein on tumor macrophages by flow cytometry and the absence of THY-1 mRNA by RNA in situ hybridization." (PMID 37388918, 2023). "Using flow cytometry, we found a distinct mApple+Thy1+ population when tri-labeled PyMT-Bo1 tumor cells were mixed with bone marrow cells." (PMID 35093137, 2022). "Taken together, these findings indicate that Thy-1 serves as a marker of fibrosis and is involved in pathways that lead to skin fibrogenesis." (PMID 36066980, 2022). "Thy-1 expression was reported in several tumor types, including liver, myeloid, skin, and brain tumors." (PMID 35563846, 2022). "The remaining six genes (e.g., PPP3CC, ITGA5, ITK, CDC25B, CCND2, and THY1) were expressed at higher levels in CD45+ TAS as compared to CD45+ tumor." (PMID 36230846, 2022). "The migration and invasion of CD326+ tumor cells and Thy1+ CAFs were reduced after injection of ApoSQ." (PMID 36241874, 2022). "Consistent with our in vitro findings, injection of ApoSQ-CAF CM inhibited the migration and invasion of CD326+ tumor cells and Thy1+ CAFs, whereas injection of WISP-1-immunodepleted ApoSQ-CAF CM did not have inhibitory effects." (PMID 36241874, 2022). "Consistent with the modeling data, tumor-derived metabolites decreased intracellular pH leading to increased expression of activation markers Pdpn and Thy1 and impacted mitochondrial behavior of FRCs in vitro and in vivo." (PMID 35362044, 2022). "It has been suggested that THY1 establishes a favorable environment that promotes tumor progression, which can be mediated by high levels of PD-L1 in CD90+ cells." (PMID 35626021, 2022). "Except for tumor cells, THY1 has also been observed in stromal cells, like ECs and CAFs, but not CD45+ cells." (PMID 35071018, 2021). "Consistent with prior reports, CD24+Thy1+ tumor cells were enriched ~ 10-fold for TICs compared to non-CD24+Thy1+ tumor cell subsets." (PMID 34088357, 2021). "Among them, THY1 (Thy-1 cell surface antigen) was selected as the key gene and was shown to be related to tumor stage, survival, and immune states of LUAD patients." (PMID 35071018, 2021). "Last mentioned model has been utilized in molecular ultrasound imaging due to the expression of Thy1 or VEGFR2 on its tumor neovasculature." (PMID 33532585, 2021). "THY-1 is a renal differentiation marker and is useful in the characterization of tumours of renal origin." (PMID 34358255, 2021). "Especially, ICAM1, THY1, and CXCR4 showed strongly positive correlations with tumor-associated macrophages." (PMID 34113647, 2021). "These tumor associated fibroblasts (TAFs) are characterized by high levels of smooth muscle actin (alpha SMA), fibroblast activation protein (FAP), Thy-1, desmin, and S100A4 protein expression." (PMID 35047489, 2021). "THY1 also regulates cancer cell proliferation, tumor metastasis, and angiogenesis, playing a dual role as a tumor promoter or suppressor." (PMID 33287223, 2020). "In particular, the myofibroblast (Thy1+/Dcn+/Acta2+ (αSMA)) fraction which comprised 4.8% of all cells in the original tumor increased to 15.9% of the tumoroid cells." (PMID 32183351, 2020).